IDO1 (indoleamine 2,3-dioxygenase 1)
Diseases named in the same sentence as IDO1 in open-access papers (continued):
Sharing a sentence is not in itself a finding about the gene and the disease.
glioma (continued). "IDO1 showed increased expression in mesenchymal and classical GBMs compared with proneural GBMs, and was higher in IDH wild-type than in IDH mutant gliomas." (PMID 33673104, 2021). "TOX had high correlation with CD276, IDO1, PDCD1LG2, and VTCN1 in both pan-glioma analysis and GBM alone." (PMID 32762688, 2020). "The expression of IDO1/TDO was positively correlated with the expression of aquaporin 4 (AQP4), implying the potential involvement of IDO1/TDO in glioma cell motility." (PMID 32296044, 2020). "Mechanistically, we found that IDO1/TDO accounted for the release of Kyn, which activated AhR to promote cell motility via the Kyn–AhR–AQP4 signaling pathway in U87MG glioma cells." (PMID 32296044, 2020). "Immunohistochemistry staining was used to measure the expression levels of IDO1, IDO2, and TDO in paraffin-embedded tissue sections of 75 glioma tissue donors." (PMID 32296044, 2020). "The expression pattern of IDO1 and its isozymes in U87MG and U251 cells was similar, and the U87MG glioma cell line was chosen for further study." (PMID 32296044, 2020). "Our study provides new evidence that supports the contribution of IDO1 in addition to TDO to glioma malignancy, highlighting the therapeutic potential of IDO1 and TDO inhibitors in the treatment of gliomas." (PMID 32296044, 2020). "The expression levels of IDO1, TDO, AhR, and AQP4 in the tumor areas of GL261 orthotopic glioma mice were higher than those in the corresponding brain tissue from healthy mice." (PMID 32296044, 2020). "All the data indicated that both IDO1 and TDO contributed to the production of Kyn, which upregulated AhR expression in glioma cells." (PMID 32296044, 2020). "TOX was strongly correlated with CD276, IDO1, PDCD1LG2 (PD-L2), and VTCN1 in pan-glioma analysis and GBM alone in both TCGA and CGGA cohorts." (PMID 32762688, 2020). "In this study, the expression profiles of IDO1, IDO2, and TDO in paraffin-embedded tissue sections and the total activity of IDO1, IDO2, and TDO in serum samples from glioma patients at different pathologic grades were investigated." (PMID 32296044, 2020). "Here, we revealed that the high IDO1 mRNA expression in glioma was positively correlated with IDH-WT and 1p/19q non-codeleted subtype, respectively." (PMID 39863603, 2025). "Moreover, Kaplan–Meier survival analysis of patients with glioma from TCGA and CGGA databases revealed that OS was significantly lower for patients with IDO1-high expression than for those with IDO1-low expression." (PMID 39863603, 2025). "Although the combination of RY103 and TMZ had no synergistic effect on glioma and was not an ideal treatment strategy for glioma, it was the first trial on the combination of our novel IDO1 inhibitor and a standard therapeutic agent." (PMID 39065567, 2024). "Glioblastomas are notable for high expression of the tryptophan catabolising enzymes indole-2,3-dioxygenase-1 (IDO-1) and tryptophan-2,3-dioxygenase-2 (TDO2); moreover, high expression of these enzymes strongly correlates with glioma severity and poor patient survival." (PMID 39048947, 2024). "In summary, the IDO1 inhibitor RY103 showed good therapeutic efficacy in terms of KP blockage and Treg reduction, suggesting that RY103 had promising therapeutic potential as a treatment for glioma." (PMID 39065567, 2024). "We compared the therapeutic effects of RY103 with IDO1 selective inhibitor INCB, and TMZ, a standard chemotherapeutic agent for malignant glioma, as well as the combination of RY103 with TMZ in GL261 orthotopic glioma-bearing mice." (PMID 39065567, 2024). "In such models, glioma cell lines are typically implanted stereotaxically into the brains of mice to create an orthotopic glioma tumour and are then treated with vehicle or TMZ alone in conjunction with a test article IDO1 inhibitor." (PMID 39048947, 2024).
glioma (continued). "Based on the significant correlation between tryptophan metabolism and glioma development as well as TMZ efficacy, we speculate that IDO1 and AHR are the potential targets in bacterial tryptophan metabolism." (PMID 36927689, 2023). "IDO1 and TDO2 are highly expressed in glioma cells proportionally to glioma grade." (PMID 36900311, 2023). "A recent study has pointed out that instead of IDO1, interleukin 4 induced 1 (IL4I1) is the novel and the main Trp‐catabolic enzyme in glioma and chronic lymphocytic leukemia, which explains the major reason why the clinical trials of IDO1 inhibitors are a failure." (PMID 37655051, 2023). "Besides, we also made an analysis of the relationship between differential LOXs expressions and the expressions of immune checkpoints including PD-L1, PD-1, IDO-1, and CTLA4 in glioma." (PMID 36160460, 2022). "Meanwhile indoleamine 2,3-dioxygenase (IDO)-1/2 and tryptophan 2,3-dioxygenase (TDO)-2 were highly expressed in glioma cells and were proportional to tumor grade, which catalyzed the decomposition of Trp into kynurenine (Kyn), a ligand of the aryl hydrocarbon receptor (AHR)." (PMID 34211978, 2021). "First, we investigated the expression of IDO1, IDO2, and TDO in different human glioma cell lines." (PMID 32296044, 2020). "For the first time, we demonstrated that the IDO1/TDO–Kyn–AhR signaling pathway could regulate AQP4, which is involved in the migration and invasion of glioma cells." (PMID 32296044, 2020). "In conclusion, using clinical samples, we found that the expression and activity of IDO1/TDO rather than IDO2 contribute to the malignancy of glioma." (PMID 32296044, 2020). "In IDO1-, IDO2-, and TDO-expressing glioma tissue samples, it was found that the expression of IDO1 and TDO rather than IDO2 was positively correlated with the pathologic grades." (PMID 32296044, 2020). "In contrast to IDO1, whose regulation has been thoroughly characterized and involves tumor suppressor genes, oncogenes, growth factor/cytokine signaling pathways, and epigenetic mechanisms, the regulation of TDO2 in gliomas is not well understood." (PMID 32477324, 2020). "The enzymatic degradation of tryptophan (Trp) to kynurenine (Kyn), mediated by indoleamine-2,3-dioxygenase-1 (IDO1) or tryptophan-2,3-dioxygenase (TDO2), is a key immunosuppressive pathway operative in gliomas and other types of tumors, and an emerging drug target in cancer immunotherapy." (PMID 32477324, 2020). "RY103, an IDO1/TDO dual inhibitor, could block the IDO1/TDO–Kyn–AhR–AQP4 signaling pathway and exert anti-glioma effects in GL261 orthotopic glioma mice." (PMID 32296044, 2020). "Thus, the total activity of IDO1 and TDO was inhibited by the IDO1/TDO dual inhibitor RY103 in GL261 orthotopic glioma mice." (PMID 32296044, 2020). "In this study, using paraffin-embedded tissue sections from patients with glioma (75 cases) at different pathologic grades, it was found that the expression of IDO1/TDO rather than IDO2 was positively correlated to the pathologic grades of gliomas." (PMID 32296044, 2020). "Moreover, evidence has emerged to suggest that upregulated IDO1 and TDO2 expression within the tumor was correlated with decreased OS of patients with glioma." (PMID 28389631, 2017). "For these targets, the human glioma LN-18 cell line was used to evaluate downregulation activity due to its high expression level of IDO-1, PDL1, and TGF-β2 with or without induction by IFNγ." (PMID 28325288, 2017). "The significantly higher IDO-2 expression in IFN-γ stimulated glioma cells compared to unstimulated, may suggest that IDO-2, like IDO-1 can be potentiated by IFN-γ." (PMID 25415278, 2014). "Aside from IDO1, IDO2, and TDO are also tryptophan catabolic molecules co-expressed by glioma." (PMID 23720663, 2013). "Likewise, PCC0208009, a potent IDO1 inhibitor, significantly synergised with TMZ to reduce subcutaneous GL2612 tumour growth in mice and improved survival in a C6 orthotopic rat model of glioma." (PMID 39048947, 2024).
glioma (continued). "Thus, the total activity of IDO1 and TDO was increased in GL261 orthotopic glioma mice." (PMID 32296044, 2020). "Therefore, IDO1 or TDO expression or IDO1 and TDO coexpression could be used as independent prognostic factors for the overall survival of glioma patients." (PMID 32296044, 2020). "Collectively, these data suggest that, in addition to IDO1, IDO2 and TDO may also be high-impact targets for investigating their contribution to modulating Treg levels, as well as overall future therapeutic possibilities for glioma patients." (PMID 23720663, 2013). "Therefore, it would be interesting to investigate whether IDO1 could deplete Trp, thereby activating the GCN2 pathway, which can be detected using C/EBP homologous protein (CHOP) as a marker, and upregulating VEGFA expression in glioma." (PMID 39065567, 2024). "IDO1-overexpression-derived-tryptophan depletion activated the general control nonderepressible 2 (GCN2) pathway and upregulated VEGFA in glioma cells." (PMID 39065567, 2024). "Herein, by using clinical samples, we found that the expression and activity of IDO1 and/or TDO (IDO1/TDO) rather than IDO2 were positively correlated with the pathologic grades of gliomas." (PMID 32296044, 2020). "Interestingly, the peripheral IDO does not directly affect T cell infiltration into the glioma tissue, but cells within the GME expressing IDO-1 drive the intra-tumoral accumulation of Tregs." (PMID 37046685, 2023).
lung carcinoma (121 papers, 2006 to 2026). "IDO1 serves as a prognostic biomarker, effectively predicting metastatic risk and survival outcomes in lung cancer." (PMID 41332472, 2025). "The clinical relevance of the IDO1-AHR-IL6-STAT3 transcriptional circuit is underscored by the associations of high IDO1 expression with reduced relapse-free survival in lung carcinoma patients." (PMID 40789452, 2025). "Recent studies have shown that IDO1-associated Try metabolites are strongly associated with the development of lung cancer." (PMID 38558328, 2024). "High expression of IDO1 has been observed in various malignant tumors including lung cancers and its overexpression is associated with unfavorable clinical outcomes." (PMID 37061716, 2023). "IDO1 is highly expressed in various malignant tumors including lung cancer, and its overexpression is linked to unfavorable clinical outcomes." (PMID 38149244, 2023). "Furthermore, IDO1‐deficient mice are partially resistant to cancer growth in a Lewis rat model of lung carcinoma." (PMID 34422661, 2021). "Actually, the IDO1-related Try metabolites are associated with lung cancer development." (PMID 34422661, 2021). "Furthermore, IDO1 has been suggested as a target in lung cancer since its expression is associated with the microvessel density." (PMID 32776284, 2020). "Because we observed that the up-regulation of IDO1 in lung cancer is a frequent event and closely associated with lung cancer metastasis, we postulated that increased IDO1 in lung cancer cells may impose positive effects on cell invasion and metastasis." (PMID 28903363, 2017). "Indoleamine 2,3-dioxygenase 1 (IDO1), a key enzyme in tryptophan (Trp) metabolism, is often upregulated in cancers, but its specific role in driving lung cancer-associated cachexia remains inadequately defined." (PMID 42028912, 2026). "Myricetin was found to directly bind to Jak1 and has been reported to prevent the phosphorylation of STAT1 and inhibit both the expression and nuclear translocation of IRF1 to suppress IFN-γ-induced IDO1 expression in human lung cancer cells." (PMID 40002369, 2025). "PD-L1 and IDO-1 are differentially expressed in human lung carcinomas and have distinct staining patterns." (PMID 40475772, 2025). "TDO2 is expressed in various cancers, and Perez‐Castro's analysis of tumor mRNA in TCGA revealed a downregulation of IDO1 along with an upregulation of TDO in lung cancer." (PMID 40103267, 2025). "Despite the increasing interest reported in the literature about IDO-1 and its correlation with immune suppression in cancer, scant information exists up to now regarding the expression of IDO-1 in lung cancer." (PMID 40475772, 2025). "In a lung cancer study, it was found that the impaired differentiation and function of DCs was due to tryptophan degradation, which was caused by both CAF-released IDO1 and lung-cancer-derived galectin-1-induced tryptophan 2,3-dioxygenase (TDO2)." (PMID 40805183, 2025). "IDO2, the isoenzyme of IDO1, is overexpressed in non‐small cell lung cancer, pancreatic cancer, and cervical cancer." (PMID 40103267, 2025). "IDO1 has been identified as a key marker in the IFNγ signature, as well as other gene signatures predictive of response to ICIs in lung cancer." (PMID 39015091, 2024). "Some data have been reported for IDO1, which was demonstrated to have a pro-angiogenic role in ovarian types and to be involved in vasculogenic mimicry of lung cancer cells." (PMID 38794128, 2024).
lung carcinoma (continued). "In a mouse model of lung cancer, silencing IDO1 inhibited tumor growth by reversing T cell exhaustion." (PMID 39726592, 2024). "It is suggested that IDO1 is an important target for regulating tryptophan metabolism in the lung cancer microenvironment to improve the efficacy of PD-1 inhibitors." (PMID 38882349, 2024). "High levels of B7-H3, B7-H4, IDO1, and EphA2 expression in lung cancer are correlated to a poor prognosis." (PMID 38267913, 2024). "Generally, suppressing the STAT1/IDO1-mediated tryptophan-kynurenine pathway is regarded as an important strategy of QFM combined with PD-1 inhibitors against lung cancer." (PMID 38882349, 2024). "Wu and colleagues recently reported that platinum-resistant non–small cell lung cancer tumors harnessed TRP catabolism via IDO1 and TDO2 to promote cell survival and immune evasion." (PMID 38451784, 2024). "We chose to study HCC827 and H1792 cell lines since they had the highest induction of IDO1 among the lung cancer cell lines studied and they form spontaneous spheroids in low attachment conditions." (PMID 37985999, 2023). "Our study shows that IDO1 and IDO1’s product Kyn are elevated in lung cancer cells exposed to IL-1β." (PMID 37985999, 2023). "To gain better insights into the biological effects of IL-1β in lung cancer cells, we used the TCGA database to identify genes that are co-expressed with IDO1 in lung adenocarcinoma patients." (PMID 37985999, 2023). "Nevertheless, the IL-1β induction of IDO1 and its product Kyn is likely to reduce the growth of lung cancer cells in vivo due to the ability of Kyn to blunt T-cells activity and allow for immune evasion." (PMID 37985999, 2023). "Elevated levels of PD-L1 and IDO1 in NSCLC patients have been shown to be associated with the infiltration of B and T cells, and potentially affect the immune escape of lung cancer cells." (PMID 36308553, 2023). "Targeting of IDO1 via RY103, a novel IDO1 inhibitor, improved NK cell-mediate anti-tumor activity in xenograft mouse models of lung cancer." (PMID 37876966, 2023). "The Kyn : Trp ratio in serum of lung cancer patients is widely used to reflect the activity of IDO1 with minimal invasiveness." (PMID 36824664, 2023). "Evidence showed that IDO-1 not only participates in the immune escape process of lung cancer but also contributes to the safety of the pretumor area." (PMID 35872931, 2022). "Research reported that IDO1 is important for supporting lung cancer development, consistent with its role in inducing T cell tolerance." (PMID 36032151, 2022). "First, we investigated in vitro the changes in IDO-1 gene expression (measuring mRNA levels by PCR) induced by IFNγ stimulation, in a panel of lung cancer cells, classified as epithelial or mesenchymal, according previously published EMT score." (PMID 36419183, 2022). "Interferon-induced guanylate-binding protein 1 (GBP1)-mediated extracellular secretion of IDO1 stimulates the progression of lung cancer cells." (PMID 34201791, 2021). "Again, many of the immune-modulatory genes differentially expressed in the mouse model were site-specifically recapitulated, e.g., higher CCL2, CXCL5, CXCL9, CXCL11, CXCL14, CXCL17, and IDO1 in lung cancers and higher CXCL12, FGL1, and LAG3 in liver cancers." (PMID 33985562, 2021). "Compared with lung carcinoma model rats, IDO1, IDO2, and TDO protein levels in the lung tissue of normally fed rats and IDO inhibitor–intervened rats reduced evidently (P < 0.05)." (PMID 34399782, 2021). "IDO-1 exerts a potent immunosuppressive effect through inhibiting T-lymphocytes and other immune cells; additionally, IDO-1 has been shown to induce favorable tumor progression in animal models of lung cancer." (PMID 33671892, 2021). "Another study of lung cancer indicated that both CAF-released IDO1 and tryptophan 2,3-dioxygenase (TDO2) induced by lung cancer-derived galectin-1 are responsible for the impaired differentiation and function of DCs through the degradation of tryptophan." (PMID 34635121, 2021).